RNASEH2B-AS1 (RNASEH2B antisense RNA 1)
Gene: Long non-coding RNA gene on chromosome 13 (50,862,172 to 50,910,789, reverse strand). Ensembl gene ENSG00000233672.
Gene Ontology:
Biological process: SRP-dependent cotranslational protein targeting to membrane, signal sequence recognition
Cellular component: signal recognition particle, endoplasmic reticulum targeting